CISD1 (CDGSH iron sulfur domain 1)
Diseases named in the same sentence as CISD1 in open-access papers (continued):
Sharing a sentence is not in itself a finding about the gene and the disease.
lung adenocarcinoma (5 papers, 2021 to 2023). A carcinoma that arises from the lung and is characterized by the presence of malignant glandular epithelial cells. "CISD1 is up-regulated in lung adenocarcinoma, and CISD1 knockdown is noted to significantly inhibit lung adenocarcinoma cell proliferation." (PMID 36497343, 2022). "Our study identified a novel m6A-related ferroptosis-associated six-gene signature (comprising SLC2A1, HERPUD1, EIF2S1, ACSL3, NCOA4, and CISD1) for predicting lung adenocarcinoma prognosis, yielding a useful prognostic biomarker and potential therapeutic target." (PMID 37072786, 2023). "The study reported that the ferroptosis-related GSEC- lncRNA/mirNA-101-3P/CISD1 axis could be an independent prognostic marker for lung adenocarcinoma." (PMID 37228500, 2023).
lung carcinoma (4 papers, 2021 to 2025). "In summary, we identified that the four ferroptosis suppressor genes, ACSL3, CISD1, FANCD2, and SLC3A2, could increase the cancer stemness, indicating that the lower the ferroptosis level in lung cancer cells, the higher the tumor heterogeneity." (PMID 34434214, 2021).
Wolfram syndrome (4 papers, 2019 to 2023). Wolfram syndrome (WS) also known as DIDMOAD, is a neurodegenerative disorder characterized by type I diabetes mellitus (DM), diabetes insipidus (DI), sensorineural deafness (D), bilateral optical atrophy (OA) and neurological signs. "Our findings reveal that CISD-1 serves as a mechanistic link between autophagy and the apoptotic pathway in mitochondria to differentially modulate organismal proteostasis and ageing, and suggest novel approaches which could facilitate the treatment of Wolfram Syndrome or related diseases." (PMID 36774344, 2023). "Interestingly, CISD1 (CDGSH iron sulfur domain 1) also associated with LCT; CISD1 is a mitochondrial protein reduced in cystic fibrosis, the deficiency of which may cause Wolfram syndrome with neurodegeneration." (PMID 33920682, 2021).
Obesity (3 papers, 2018 to 2021). Accumulation of substantial excess body fat. "Because mitoNEET (also called CISD1), a mitochondrial outer membrane protein, has been implicated in the action of pioglitazone in PVAT, we conducted a series of experiments to examine the role of mitoNEET in attenuation of obesity-mediated arterial stiffness by pioglitazone." (PMID 33781257, 2021).
pancreatic cancer (3 papers, 2022 to 2025). "To clarify the functional role of signature genes in PAAD cells, we used Cancer Cell Line Encyclopedia (CCLE) database to analyze the expression of ALOX5, ALOX12 and CISD1 in pancreatic cancer cells, and found that the expression of ALOX5 was relatively highly expressed in T3M4 cells." (PMID 35033072, 2022). "CISD1 was also regarded as a potentially effective tool for prognostic of pancreatic cancer." (PMID 35309947, 2022). "The results obtained with qPCR and IHC assays showed that ALOX5 was highly expressed regardless of whether ALOX12 and CISD1 were expressed at low levels in these pancreatic cancer tissue samples." (PMID 35033072, 2022).
asthma (2 papers, 2023 to 2024). "Through validation, we found that CAMKK2 and CISD1 expression were upregulated in the asthma group compared to the control group and would inhibit the occurrence of ferroptosis." (PMID 36843917, 2023). "Similar results were also obtained in the GSE143303 dataset, CAMKK2 was significantly downregulated in the asthma group, and CISD1 was significantly upregulated in the asthma group (p < 0.05)." (PMID 36843917, 2023). "In the present study, we found that CISD1 was significantly upregulated in the asthma group compared to healthy controls in asthmatic or OVA mice." (PMID 36843917, 2023). "CAMKK2 and CISD1 are key suppressors of iron-induced cell death in asthma." (PMID 38783263, 2024). "We discovered that CAMKK2 and CISD1 were crucial ferroptosis suppressors in asthma." (PMID 36843917, 2023). "We discovered CAMKK2 and CISD1 were ferroptosis-related key genes for asthma patients, which could provide a reference for immunotherapies and targeted therapies." (PMID 36843917, 2023). "CISD1 was significantly upregulated and CAMKK2 was downregulated in both mild to moderate asthma and severe asthma compared to healthy controls in the GSE147878 dataset (p < 0.05), which was consistent with the results of this study." (PMID 36843917, 2023). "We found CISD1 was significantly upregulated and CAMKK2 was downregulated in both mild to moderate asthma and severe asthma compared to healthy controls." (PMID 36843917, 2023). "Our study was the first to find that upregulated CISD1 and CAMKK2 inhibited ferroptosis and played an important regulatory role in asthma." (PMID 36843917, 2023). "Therefore, we verified the expression of CISD1 and CAMKK2 in mild/moderate asthma and severe asthma." (PMID 36843917, 2023). "However, no studies were conducted to explore the role CISD1 plays in asthma." (PMID 36843917, 2023).
B-cell acute lymphoblastic leukemia (2 papers, 2022). A neoplasm of lymphoblasts committed to the B-cell lineage, typically composed of small to medium-sized blast cells. "It had been reported that loss of CISD1 could inhibit B-cell acute lymphoblastic leukemia cells proliferation." (PMID 36671422, 2022). "CISD1 may suppress ferroptosis by inhibiting iron uptake by mitochondria and CISD1 inhibition by small molecular ligand NL-1, which is reported to overcome drug resistance and exert anti-leukemic activity in B-cell acute lymphoblastic leukemia." (PMID 34784264, 2022).
breast tumor (2 papers, 2022 to 2025). "Simultaneously, we exhibited that SB-T-101141 triggered a novel ferroptosis to repress breast tumor growth by stably binding to KHSRP to inhibit the expression of CISD1 related to iron homeostasis." (PMID 40389408, 2025).
prostate carcinoma (2 papers, 2022 to 2025). A carcinoma that arises from epithelial cells of the prostate gland. "In addition, CISD1 expression was also significantly lower in myeloma, skin cancer, and testicular cancer compared with normal tissues and significantly higher in cervical squamous cell carcinoma, ovarian cancer, prostate cancer, and uterus cancer compared with normal tissues." (PMID 35313629, 2022).
type II diabetes (2 papers, 2022 to 2023). "Treatment with pioglitazone, originally a type II diabetes medication that targets CISD1, inhibits IP3R-CISD1 binding and rescues the PD-related phenotypes of PINK1 and Parkin null Drosophila mutants." (PMID 37626046, 2023).
acute kidney injury (1 paper, 2023). Sudden and sustained deterioration of the kidney function characterized by decreased glomerular filtration rate, increased serum creatinine or oliguria. "The Fe–S-binding proteins mitoNEET (also known as CISD1) and NAF1 (also known as CISD2), which have been shown to participate in mitochondrial iron transport, inhibit ferroptosis by protecting mitochondria from lipid peroxidation in cancer cells and acute kidney injury." (PMID 37770442, 2023).
atherosclerosis (1 paper, 2022). A disease characterized by the build-up of fatty material and calcium deposition in the arterial wall resulting in partial or complete occlusion of the arterial lumen. "On the other hand, over expressed CISD1 could attenuate atherosclerosis, helped to improve hypoxic–ischemic injury." (PMID 36671422, 2022).
cerebral infarction (1 paper, 2021). An ischemic condition of the brain, producing a persistent focal neurological deficit in the area of distribution of the cerebral arteries. "Therefore, KO-miR-127-3p can inhibit autophagy and cerebral infarction by upregulating CISD1 protein." (PMID 33723216, 2021).
Crohn disease (1 paper, 2020). A gastrointestinal disorder characterized by chronic inflammation involving all layers of the intestinal wall, noncaseating granulomas affecting the intestinal wall and regional lymph nodes, and transmural fibrosis. "The CDGSH iron-sulfur domain 1, CISD1, and serologically defined colon cancer antigen 3, SDCCAG3, genes are associated with both ulcerative colitis and Crohn’s disease." (PMID 32375333, 2020).
heart failure (1 paper, 2022). Inability of the heart to pump blood at an adequate rate to meet tissue metabolic requirements. "Additionally, deficient CISD1 played a role in aged mice with heart failure." (PMID 36671422, 2022).
inflammatory bowel disease (1 paper, 2025). A spectrum of small and large bowel inflammatory diseases of unknown etiology. "One such example is the CISD1 gene associated with inflammatory bowel diseases (IBD)." (PMID 40208878, 2025).
injury (1 paper, 2021). Damage inflicted on the body as the direct or indirect result of an external force, with or without disruption of structural continuity. "Moreover, miR-127-3p and/or CISD1 could be considered as potential targets for the therapy of neonatal HI brain injury in future clinic practice." (PMID 33723216, 2021).
Iron deficiency (1 paper, 2024). "However, sorafenib resistance is shown to be associated with highly expressed CISD1 as along with iron deficiency." (PMID 38918793, 2024). "Iron deficiency is associated with sorafenib resistance in HCC, moreover, CISD1 has been reported to be induced by erastin to inhibit ferroptosis by protection against mitochondrial lipid peroxidation." (PMID 38918793, 2024).
ischemia (1 paper, 2021). A hypoperfusion of the BLOOD through an organ or tissue caused by a PATHOLOGIC CONSTRICTION or obstruction of its BLOOD VESSELS, or an absence of BLOOD CIRCULATION. "Among them, CISD1 is a mitochondrial membrane protein and contains the iron ion transport domain, which plays an important role in the regulation of mitochondrial iron ion transport and oxidative stress, and is closely related to the HI of neurons after ischemia." (PMID 33723216, 2021).
melanoma (1 paper, 2022). A malignant, usually aggressive tumor composed of atypical, neoplastic melanocytes. "In contrast, ALOX5, CISD1, ATP5MC3, NFS1, EMC2, ZEB1 are highly expressed in normal tissues, and they are related to the good prognosis of melanoma patients." (PMID 36313708, 2022).
psoriasis (1 paper, 2022). An autoimmune condition characterized by red, well-delineated plaques with silvery scales that are usually on the extensor surfaces and scalp. "Besides, based on CIBERSORT analysis, alterations of immune microenvironment in psoriasis cases were possibly associated with PRKAA2, PEBP1, CISD1, and ACSF2." (PMID 36685512, 2022). "Typically, ABCC5 (p = 0.0012), CISD1 (p= 3.9e−10) and TRIB2 (p < 2.22e−16) levels in psoriasis cases increased compared with healthy samples, whereas NR5A2 (p = 1.8e−13), PEBP1 (p < 2.22e−16) and PRKAA2 (p < 2.22e−16) levels decreased in psoriasis samples." (PMID 36685512, 2022). "Typically, CISD1 (p = 3.9e-10), TRIB2 (p < 2.22e−16), and ABCC5 (p=0.0012) levels among psoriasis cases increased compared with healthy controls, whereas PRKAA2 (p < 2.22e−16), ACSF2 (p = 3e−15), TIMM9 (p= 0.049), PEBP1 (p < 2.22e−16) and NR5A2 (p=1.8e−13) levels decreased among psoriasis cases." (PMID 36685512, 2022).
sarcopenia (1 paper, 2022). Progressive decline in muscle mass due to aging which results in decreased functional capacity of muscles. "In this study, seven genetic biomarkers closely associated with sarcopenia, such as CISD1, ETNPPL, and WISP2, were identified by RF and were used to construct a diagnostic prediction model for sarcopenia with high diagnostic performance." (PMID 36050999, 2022). "Surprisingly, during the analysis to construct the diagnostic model of sarcopenia, three key genes (CISD1, ETNPPL, and WISP2) that might play a vital role in the pathogenesis were identified for the first time." (PMID 36050999, 2022). "Therefore, we speculated that the imbalance of iron homeostasis caused by the decreased expression of CISD1 might be implicated in the pathogenesis of sarcopenia." (PMID 36050999, 2022). "The proteins encoded by three of these genes (CISD1, ETNPPL, and WISP2) may be potential biomarkers for sarcopenia." (PMID 36050999, 2022). "Furthermore, the heat map of key DEGs revealed that the expression of CISD1 in the sarcopenia group was significantly lower than that in the normal group, indicating that iron overload might be present in the mitochondria of skeletal muscle cells of sarcopenic patients." (PMID 36050999, 2022).
systemic lupus erythematosus (1 paper, 2022). An autoimmune multi-organ disease typically associated with vasculopathy and autoantibody production. "Enrichment analysis results showed that these co-expressed genes with CISD1 contributed mostly to systemic lupus erythematosus, taste transduction, and other pathways, which in turn improved that CISD1 was related to immune system function from another perspective." (PMID 36671422, 2022).
cancer (31 papers, 2018 to 2025). A tumor composed of atypical neoplastic, often pleomorphic cells that invade other tissues. "Although the results highlighted that CISD1 expression levels have varying impacts on overall survival across different cancer types, high CISD1 expression is generally associated with worse survival." (PMID 40831536, 2025). "Our findings demonstrate CISD1 as a reliable and promising diagnostic, prognostic, and immunotherapeutic biomarker for multiple cancers, emphasizing its crucial role in cancer biology and potential to guide personalized cancer therapies." (PMID 40831536, 2025). "Using SangerBox online analysis, we further explored the mutation types and mutation sites of CISD1 and found that missense mutations were the main type of CISD1 mutation in cancer." (PMID 40831536, 2025). "Even with opposing expression levels in different cancers, CISD1 can still provide meaningful diagnostic, prognostic, or predictive information from our findings." (PMID 40831536, 2025). "Given the association between cancer stem cell-related stemness indices and poor patient outcomes, the correlation with CISD1 highlights its potential as a prognostic biomarker." (PMID 40831536, 2025). "The upregulation of either CISD1 or CISD2 reduces the susceptibility of human cancers to ferroptosis inducers by limiting mitochondrial iron uptake." (PMID 37345031, 2023). "Indeed, CISD1 is also associated with cancer stages development, as its mRNA expression levels are increased with the progress of the cancer stages and metastasis in various cancers." (PMID 40831536, 2025). "First, CISD1 can be a diagnostic biomarker to aid early detection of various cancers." (PMID 40831536, 2025). "Missense mutations were the most frequent type of CISD1 gene mutations in various cancers, highlighting that the mutations of CISD1 could be targets for diagnostic assays." (PMID 40831536, 2025). "Taken together, these results suggest that CISD1 gene alterations may regulate the initiation, growth, and progression of various cancers and can serve as a potential diagnostic biomarker." (PMID 40831536, 2025). "Overall, these results show CISD1 gene mutations, amplifications, and deletions are present in multiple cancers, with missense mutations as the most frequent type of CISD1 gene mutations in various cancers, and copy number alterations as the most frequent genomic change in most of the cancers." (PMID 40831536, 2025). "This suggests CISD1 may be involved in tumorigenesis and is a potential diagnostic biomarker for these cancer types." (PMID 40831536, 2025). "Our findings reveal significant alterations in CISD1 expression at both transcriptional and translational levels, as well as gene mutations across multiple cancers, indicating its potential as a diagnostic biomarker and its involvement in cancer development and progression." (PMID 40831536, 2025). "Overall, the association between CISD1 and cancer cell stemness varies by cancer type." (PMID 40831536, 2025). "In summary, our systematic pan-cancer analysis of CISD1, for the first time, shows that its expression is significantly altered in the vast majority of cancers analyzed." (PMID 40831536, 2025). "By modulating cancer stem cell characteristics, CISD1 not only contributes to tumor aggressiveness but also presents as a promising target for innovative therapies aimed at eradicating cancer stem cell-driven disease." (PMID 40831536, 2025). "Studies have shown that CISD1 regulates the levels of iron and reactive oxygen species in cancer cells." (PMID 40831536, 2025). "This manuscript aims to elucidate the expression patterns, genomic alterations, stemness profiles, and clinical significance of CISD1 across multiple cancer types." (PMID 40831536, 2025).